FOSL1 (FOS like 1, AP-1 transcription factor subunit)
Diseases named in the same sentence as FOSL1 in open-access papers (continued):
Sharing a sentence is not in itself a finding about the gene and the disease.
lung carcinoma (34 papers, 2012 to 2025). "FOSL1 expression, for example, was found to be inversely associated with the OS of lung cancer patients, particularly those with LUAD." (PMID 35795208, 2022). "In lung cancer, FOSL1 acts as a bridge between KRAS mutations and mitosis and its inhibition will reduce the viability of KRAS mutant cells." (PMID 34430085, 2021). "On the other hand, when FOSL1 is overexpressed, it causes an elevation in the electrical potential across the mitochondrial membrane, a reduction in the levels of ROS and Ca2+ inside the cell, and finally results in the prevention of apoptosis in lung cancer cells." (PMID 38791400, 2024). "Analysis of Gene Expression Omnibus (GEO) datasets indicated a significant upregulation of FOSL1 in lung cancer tissues relative to normal samples." (PMID 40414926, 2025). "Lung cancer cell lines displayed heightened sensitivity to FOSL1 depletion compared to JUN knockout." (PMID 40414926, 2025). "Most notably, Kaplan-Meier survival analysis of lung cancer cohorts from the Cancer Genome Atlas (TCGA) and GEO demonstrated that elevated FOSL1 expression correlates with significantly worse overall survival." (PMID 40414926, 2025). "Studies have shown that lung cancer cells with elevated FOSL1 ectopic expression demonstrated reduced apoptosis rates compared to control cells." (PMID 38791400, 2024). "These bioinformatic analyses provided further evidence on the clinical relevance between SS‐elevated gene expression of PRSS3, PAR2, and FOSL1 and lung cancer." (PMID 37395651, 2023). "FOSL1 is a transcription factor, and high expression of FOSL1 predicts poor prognosis in mutant KRAS lung cancer." (PMID 36712848, 2022). "KRT19, SPARC, SPOCK, LINC00707 (lung cancer promoting lincRNA), FOSL1 and AXL (identified as downstream targets of TS as they appeared in both signatures) were qPCR validated in both cell lines." (PMID 33024270, 2021). "FOSL1 can regulate gene expression induced by KRAS mutation, and thus control cell proliferation and survival, and predicts a poor prognosis in lung cancer." (PMID 34430085, 2021). "Among the upregulated Wnt target genes, FOSL1 is an oncogene that has recently been discovered in lung cancer and pancreatic cancer." (PMID 30613366, 2018). "The clinical relevance of α6-integrin, FOSL1 and αV-integrin upregulation was visualized by using Kaplan–Meier analysis with clinical survival data from a collection of 179 pancreatic and 516 lung cancer (adenocarcinoma) samples from TCGAbrowser, respectively." (PMID 28604746, 2017). "Strikingly, high levels of α6-integrin, FOSL1 and αV-integrin expression were all correlated with significantly reduced survival of both in pancreatic cancer and lung cancer patients when compared with patients with low level expression of the same genes." (PMID 28604746, 2017). "It is noteworthy that JQ1-dependent FOSL1 downregulation, previously reported in lung cancer, was observed in both sensitive and resistant cell lines and basal gene expression of FOSL1 was also not predictive of response to JQ1." (PMID 27607580, 2016). "Recent studies have identified other important targets of JQ1, such as FosL1 in lung cancer cell lines, or IL7R in lymphoblastic leukemia." (PMID 26397223, 2015). "FOSL1 is overexpressed in CSCs of various cancers, including breast, colorectal, and lung cancers." (PMID 38791400, 2024). "Interestingly, FOSL1 levels were found to have a positive relationship with CIB2 levels by correlation coefficient analysis using the GEPIA database in lung cancer patient samples." (PMID 39264588, 2024). "Together, these results unveil the clinical significance of PRSS3, PAR2, and FOSL1 and suggest that they may serve as new biomarkers for the diagnosis and treatment of lung cancer metastasis." (PMID 37395651, 2023). "Therefore, FOSL1 activation may serve as a potential target for human lung cancer therapy and a prognostic marker, particularly in cases with KRAS mutations." (PMID 38791400, 2024).
lung carcinoma (continued). "Likewise, FOSL1 depletion in mouse Kras-driven lung cancer cells decreased tumour volume." (PMID 28220783, 2017). "FOSL1 and MYC are oncogenic transcription factors that contribute to the development and progression of various cancer types, including lung cancer, and their expression levels have been shown to be upregulated by the EGFR-ERK1/2 signaling pathway." (PMID 39858622, 2025). "Of note, AREG, EREG, FOSL1, MYC, and PLAU are involved in the EGFR signaling pathway, which is a key pathway in lung cancer development." (PMID 39858622, 2025). "Lung cancer regulatory networks from trametinib-treated cells confirmed the strong involvement of the RAS-ERK signaling pathway and its positive influence on ETS1, FOSL1 and SMAD3." (PMID 41184222, 2025). "Moreover, five of the remaining genes showed significant results in at least one of the lung cancer types, including LRRC27 and PLEKHB1 in LUAD and ARNTL2, FOSL1, and PTBP3 in LUSC." (PMID 39410631, 2024). "In conclusion, our study first demonstrated that FOSL1/CIB2/ZEB1 pathway functioned in regulation of gefitinib resistance and CIB2 could be applied as a novel biomarker for diagnosis of drug resistance of lung cancer." (PMID 39264588, 2024). "Transcriptomic data from METex14Del-expressing cells, stimulated or not by HGF, were mapped onto this lung cancer reference network and revealed activation of a major regulatory node composed mainly by the highly influential transcription factors ETS1, FOSL1 and SMAD3." (PMID 41184222, 2025).
colon carcinoma (31 papers, 2012 to 2026). "We detected more modest inverse correlations with BMP4 and FOSL1 (but with higher conditional R2-values and high p-values); these genes are also implicated in colon cancer cell proliferation and metastasis." (PMID 35370785, 2022). "The prognostic value of Fra-1 was assessed by correlating FOSL1 mRNA levels (encoding Fra-1) in colon cancer patient samples to disease-free survival in five gene expression datasets." (PMID 26646695, 2015). "In colon cancer, miRNA-497 can inhibit FOSL1, thus reducing the content of FOSL1 and decreasing the content of miR-34a in tumor cells." (PMID 40821785, 2025). "Through functional pathway analysis, it was discovered that the Wnt pathway is central in the classifier, indicating a possible mechanism of how FOSL1 functions in colon cancer metastasis." (PMID 38791400, 2024). "For instance, esophageal and colon tumors are characterized by high levels of FOSL1 at early stages, whereas thyroid and breast tumors continue to accumulate FOSL1 even at late stages of the disease." (PMID 35163444, 2022). "FOSL1 was also found to be highly expressed in colon cancer tissues as well as ITGB4 in TCGA-colon cancer cohort." (PMID 31602273, 2019). "For example, colon carcinoma cells treated with MEK inhibitor U0126 or PD184352 had lower FOSL1 expression." (PMID 28049150, 2017). "Moreover, the FOSL1 classifier has the potential to serve as a prognostic predictor for colon cancer patients." (PMID 38791400, 2024). "Whereas, we found that ITGB4 ectopic expression might be regulated by the up-regulation of the transcription factor FOSL1, the down-regulation of miR-335-5p, and its promoter hypomethylation in colon cancer." (PMID 31602273, 2019). "The elevated ITGB4 transcription in colon cancer might due to its upstream transcription factor FOSL1 up-regulation and its promoter hypomethylation." (PMID 31602273, 2019). "However, FOSL1 inhibition experiments later unveiled a role in the control of a motility and invasion programme in human colon cancer cells expressing oncogenic KRASG13D (refs 29, 44) in vitro." (PMID 28220783, 2017). "Although BRAF V600E‐positive GBMs account for only 3% of whole cases, the BRAF‐FOSL1 axis appears to be potentially relevant, given that BRAF is the upstream signaling molecule of FOSL1 in colon cancer and that both molecules share the MAPK signaling pathway." (PMID 41556041, 2026). "Analysis of differentially methylated loci established FOSL1 and SP1/2/3 binding motifs as highly ranked for hypomethylated and hypermethylated genes respectively, in a side-independent manner within colon cancers." (PMID 32293332, 2020). "To further explore direct transcriptional targets of FRA1 in the regulation of colon cancer stemness, we analyzed NANOG protein expression in FOSL1-overexpressing DLD1 and HT-29 cells by western blot." (PMID 30804456, 2019). "Butyrate has been shown to downregulate Wnt activity in CC531 rat colon carcinoma cells by reducing the expression of 4 Wnt target genes that are upregulated in CRC [CCND1, c-MYC, FOSL1, and follistatin (FST)], but it has also been shown to induce Wnt signaling leading to stimulated apoptosis." (PMID 28077379, 2017). "The molecular regulation mechanism of ITGB4 ectopic expression in colon cancer was also explored and the results indicated that ITGB4 might be up-regulated by the transcription factor FOSL1 (FOS like 1, AP-1 Transcription Factor Subunit) and its promoter hypomethylation." (PMID 31602273, 2019).
glioma (26 papers, 2010 to 2026). A benign or malignant brain and spinal cord tumor that arises from glial cells (astrocytes, oligodendrocytes, ependymal cells). "The expression of NF-κB p65 protein is correlated with FOSL1 expression in glioma patients, and both are linked to glioma grades." (PMID 40869207, 2025). "FOSL1’s role as an oncogene in glioma progression underscores its promise as both a diagnostic marker and a feasible target for pharmacological intervention in glioma patients." (PMID 38856747, 2024). "NF-κB p65 protein expression correlates to the expression of FOSL1 in glioma patients, and both are associated with glioma grades." (PMID 38856747, 2024). "The positive association between increased FOSL1 protein expression and glioma grades strongly implicated FOSL1 protein as a diagnostic marker and potential drug target for glioma patients." (PMID 38856747, 2024). "We reported previously that TRPM7 is an indirect regulator of the FOSL1 gene where high expression of FOSL1 elevates glioma cell proliferation and invasion; FOSL1 is also associated with poor survival in GBM patients." (PMID 37642779, 2023). "The positive association between increased FOSL1 protein expression and glioma grades strongly implicated the FOSL1 protein as a diagnostic marker and a potential drug target for glioma patients." (PMID 37642779, 2023). "Our previous bioinformatic analysis from TCGA mRNA data showed that FOSL1 serves as a diagnostic and prognostic marker for glioma patients." (PMID 37642779, 2023). "As risk factors for glioma, both FOSL1 and EN2 can be considered and further verified to be regulated and targeted by hsa-miR-33a." (PMID 36061185, 2022). "It is to be noted that FOSL1 was also associated with glioma growth and invasion and was a poor prognostic factor for GBM." (PMID 36061185, 2022). "They first proved that NF1 mutations act via the NF1–MAPK–FOSL1 axis in MES gliomas as they increase FOSL1 RNA and protein expression and therefore activate the expression of the MES gene signature and inhibit the non-MES gene signature." (PMID 35008787, 2021). "High FOSL1 expression is associated with poor overall survival in lung adenocarcinoma, pancreatic adenocarcinoma, clear cell renal cell carcinoma, sarcoma, low grade glioma, glioblastoma, head and neck squamous carcinoma (HNSCC), and uveal melanoma." (PMID 41286309, 2025). "In addition, survival analysis revealed that high expression of FOSL1 was associated with poor survival in glioma patients." (PMID 39227950, 2024). "This study obtained co-expressed differential miRNA genes by analyzing glioma and skeletal muscle miRNA datasets, followed by multifactorial Cox regression analysis and stepwise regression analysis to obtain a patient survival risk regression model, which included FOSL1 and EN2." (PMID 36061185, 2022). "Overexpression of FOSL1 may cause carcinogenesis, and is a typical characteristic of glioma." (PMID 25182732, 2014). "Multiple studies have shown that FOSL1 is responsible for maintaining the growth of in vitro glioma cells and promoting glioma cell invasion." (PMID 40224547, 2025). "The reciprocal control of NF-κB and FOSL1 facilitates glioma carcinogenesis and stemness by enhancing the G1/S transition and suppressing apoptosis." (PMID 40869207, 2025). "We subsequently analyzed luciferase activity in glioma cells and compared it to the wild-type FOSL1 promoter." (PMID 40869207, 2025). "Subsequently, we performed immunohistochemistry staining for FOSL1 and NF-κB p65 utilizing rabbit polyclonal antibodies against FOSL1 and NF-κB p65 in glioma tissue microarrays (TMA) obtained from 141 glioma patients and 15 healthy controls." (PMID 40869207, 2025). "Subsequently, we examined luciferase activity in glioma cells and compared it to the wild-type FOSL1 promoter." (PMID 38856747, 2024). "Functionally, FOSL1 promotes glioma cell proliferation by impeding apoptosis and facilitating cell transition from the S phase to the G2/M phase." (PMID 38856747, 2024).
glioma (continued). "Our earlier studies uncovered a pivotal event in glioma development- the activation of FOSL1, an integral member of the AP-1 transcription factor family, by the STAT3 gene." (PMID 38856747, 2024). "To this end, after overexpressing FOSL1 in glioma cell lines A172, U87MG, and PDX-L14, we conducted Western blot analysis to assess upstream regulators of NF-κB, namely IKKβ and IκBα." (PMID 38856747, 2024). "Remarkably, the silencing of FOSL1 sensitizes glioma cancer stem cells through the downregulation of miR-27a-5p, whereas the ectopic expression of FOSL1 reduces the effectiveness of radiotherapy on apoptosis and cell viability by modulating miR-27a-5p." (PMID 38791400, 2024). "Our previous work showed that FOSL1, transactivated by the STAT3 gene, functions as a tumorigenic gene in glioma pathogenesis and acts as a diagnostic marker and potential drug target in glioma patients." (PMID 38856747, 2024). "In order to better understand how TRPM7 promotes the transcription of the FOSL1 gene to contribute to glioma stemness, we created a FOSL1 promoter and its GAS mutants." (PMID 38791400, 2024). "Next, FOSL1 expression levels were elevated by introducing FOSL1 tagged with Myc-DDK/FLAG (FOSL1-FLAG) into glioma cells, we confirmed high transfection efficiency by observing the robust expression of FOSL1 and FLAG protein in A172, U87MG, and PDX-L14 cells." (PMID 38856747, 2024). "In this study, we delved into the interaction between NF-κB and FOSL1, revealing their role in driving and propelling glioma stemness and gliomagenesis." (PMID 38856747, 2024). "A recent study on glioma showed that FOSL1 can be activated by the Ras-MEK1/2-ERK1/2 axis in MAPK signaling pathway." (PMID 39365728, 2024). "In this study, we will delineate the interaction of NF-κB, an evolutionarily conserved group of molecules, with FOSL1 in promoting glioma tumorigenesis and glioma stemness." (PMID 38856747, 2024). "FOSL1 is a key regulator of the transition from PN to mesenchymal (MES), which is associated with glioma progression." (PMID 38856747, 2024). "Our previous findings demonstrated that reducing FOSL1 expression through siFOSL1 effectively decreased glioma cell proliferation by 30.6 to 50.2% within 24 to 96 h post-transfection in A172, U87MG cells, and PDX-L14 cells." (PMID 38856747, 2024). "Immunohistochemical staining of a tissue microarray revealed that FOSL1 expression was significantly elevated in glioma tissues compared with normal brain tissues, with the highest expression in GBM tissues." (PMID 39227950, 2024). "In glioblastoma, HOTAIR accelerates tumor progression by acting as a sponge for miR-301a-3p, leading to an increase in the expression of FOSL1, a key player in glioma progression." (PMID 38791400, 2024). "Tumor progression commonly involves apoptosis inhibition and to investigate the role of the apoptotic process in GBM cells overexpressing FOSL1, glioma cells were transfected with FOSL1 for 72 h, followed by staining with annexin V and 7-AAD." (PMID 38856747, 2024). "We then conducted immunohistochemical staining for FOSL1 and NF-κB p65 using rabbit polyclonal anti-FOSL1 and NF-κB p65 in glioma tissue microarrays (TMA) derived from 141 glioma patients and 15 healthy individuals." (PMID 38856747, 2024). "To address these objectives, we transfected the three glioma cell lines with FOSL1-GFP expressing constructs to augment FOSL1 expression levels, alongside control transfections." (PMID 38856747, 2024). "Mutual regulation between NF-κB and FOSL1 contributes to glioma tumorigenesis and stemness through promoting G1/S transition and inhibiting apoptosis." (PMID 38856747, 2024). "Both our in vitro experiments and clinical observations substantiate a direct correlation between NF-κB protein expression and FOSL1 levels in gliomas." (PMID 38856747, 2024).